MYOC (myocilin)
Description:
Secreted glycoprotein regulating the activation of different signaling pathways in adjacent cells to control different processes including cell adhesion, cell-matrix adhesion, cytoskeleton organization and cell migration. Promotes substrate adhesion, spreading and formation of focal contacts. Negatively regulates cell-matrix adhesion and stress fiber assembly through Rho protein signal transduction. Modulates the organization of actin cytoskeleton by stimulating the formation of stress fibers through interactions with components of Wnt signaling pathways. Promotes cell migration through activation of PTK2 and the downstream phosphatidylinositol 3-kinase signaling. Plays a role in bone formation and promotes osteoblast differentiation in a dose-dependent manner through mitogen-activated protein kinase signaling. Mediates myelination in the peripheral nervous system through ERBB2/ERBB3 signaling. Plays a role as a regulator of muscle hypertrophy through the components of dystrophin-associated protein complex. Involved in positive regulation of mitochondrial depolarization. Plays a role in neurite outgrowth. May participate in the obstruction of fluid outflow in the trabecular meshwork.
Synonyms: GLC1A; TIGR; JOAG1; GPOA; JOAG
Tractability: Antibody: UniProt places it where antibodies can reach, with high confidence; UniProt predicts a signal peptide or a membrane-spanning region; its Gene Ontology location is reachable by antibodies, with medium confidence. PROTAC: a small molecule that binds it is known.
Gene: Protein-coding gene on chromosome 1 (171,635,417 to 171,652,688, reverse strand). Ensembl gene ENSG00000034971.
Subcellular location: Secreted; Golgi apparatus; Cytoplasmic vesicle; Secreted, extracellular space; Secreted, extracellular space, extracellular matrix; Secreted, extracellular exosome; Mitochondrion; Mitochondrion intermembrane space; Mitochondrion inner membrane; Mitochondrion outer membrane; Rough endoplasmic reticulum; Cell projection; Cell projection, cilium; Secreted (Myocilin, C-terminal fragment); Endoplasmic reticulum (Myocilin, N-terminal fragment)
Gene Ontology:
Molecular function: fibronectin binding; frizzled binding; myosin light chain binding; protein binding; receptor tyrosine kinase binding
Biological process: negative regulation of cell-matrix adhesion; negative regulation of Rho protein signal transduction; negative regulation of stress fiber assembly; neuron projection development; non-canonical Wnt signaling pathway; osteoblast differentiation; positive regulation of cell migration; positive regulation of focal adhesion assembly; positive regulation of JNK cascade; positive regulation of mitochondrial depolarization; positive regulation of phosphatidylinositol 3-kinase/protein kinase B signal transduction; positive regulation of stress fiber assembly; positive regulation of substrate adhesion-dependent cell spreading; regulation of MAPK cascade; bone development; clustering of voltage-gated sodium channels; ERBB2-ERBB3 signaling pathway; myelination in peripheral nervous system; signal transduction; skeletal muscle hypertrophy
Cellular component: cytoplasmic vesicle; extracellular exosome; extracellular region; Golgi apparatus; mitochondrial inner membrane; mitochondrial intermembrane space; mitochondrial outer membrane; mitochondrion; rough endoplasmic reticulum; endoplasmic reticulum; node of Ranvier; cilium
Genetic constraint (gnomAD): Loss-of-function variants: 30 observed, 30.29 expected, observed/expected ratio (o/e) 0.99, 90% interval 0.74 to 1.34. The upper end of that interval is the gene's LOEUF score, 1.34, which puts it in group 5 of 6, group 1 being the genes least tolerant of losing a copy. Missense variants: 569 observed, 652.49 expected, observed/expected ratio (o/e) 0.87, 90% interval 0.81 to 0.94. Synonymous variants: 240 observed, 259.01 expected, observed/expected ratio (o/e) 0.93, 90% interval 0.83 to 1.03.
Gene-disease validity (ClinGen):
ClinGen rates the evidence that MYOC causes each of these diseases.
open-angle glaucoma (autosomal dominant): Definitive. Chronic outflow obstruction of the eye's drainage canals that can lead to increased internal eye pressure and optic nerve damage.
Homologues: Orthologues: chimpanzee MYOC (99% identical), macaque MYOC (95% identical), rabbit MYOC (84% identical), dog MYOC (81% identical), rat Myoc (81% identical), guinea pig MYOC (80% identical), mouse Myoc (80% identical), pig MYOC (80% identical), tropical clawed frog myoc (50% identical), zebrafish myoc (42% identical). Paralogues in human: OLFML2A (26% identical), OLFM1 (25% identical), OLFM2 (25% identical), OLFML2B (24% identical), OLFM3 (24% identical), OLFML3 (20% identical), OLFM4 (20% identical), OLFML1 (19% identical), GLDN (17% identical).
Diseases named in the same sentence as MYOC in open-access papers:
MYOC is named in the same sentence as 76 diseases in open-access papers, as found by Europe PMC text mining. Sharing a sentence is not in itself a finding about the gene and the disease. The quoted sentences say what the papers report.
glaucoma (291 papers, 2007 to 2026). Increased pressure in the eyeball due to obstruction of the outflow of aqueous humor. "Glaucoma exhibits a complex pathogenesis, with MYOC gene mutations representing significant genetic risk factors for this condition." (PMID 41328347, 2026). "MYOC is a common pathogenic gene for primary open-angle glaucoma and olfactomedin domain of MYOC participates in protein-protein interactions, which are associated with inflammatory bowel disease." (PMID 40808558, 2026). "Mutations in MYOC, the most common genetic cause of glaucoma, cause misfolded myocilin to accumulate in the endoplasmic reticulum (ER), leading to trabecular meshwork (TM) dysfunction, elevated intraocular pressure, and progressive vision loss." (PMID 41657308, 2026). "MYOC-associated JOAG is a more aggressive form of glaucoma, characterized by high IOP in young children and rapid progression to vision loss." (PMID 39836483, 2025). "Mutations in the MYOC gene, which encodes the glycoprotein myocilin (MYOC), are a well-established cause of ocular hypertension and glaucoma, particularly POAG." (PMID 41227293, 2025). "Building on these advances, our laboratory is now focused on designing and optimizing LNP formulations for targeted and efficient delivery of Cas9 mRNA to the TM, with the goal of editing disease-causing MYOC mutations in a mouse model of glaucoma." (PMID 41210166, 2025). "Current management of myocilin-associated glaucoma in the clinic is the same as age-onset OAG, which involves lowering IOP." (PMID 39726989, 2025). "MYOC is mainly linked to glaucoma and has received limited research attention in the context of cancer." (PMID 40475773, 2025). "It has also been documented that myocilin expression is more important in the TM of patients with glaucoma and that specific mutations in the MYOC gene can increase the risk of developing glaucoma." (PMID 39847376, 2025). "To better understand the factors influencing susceptibility to glaucoma, we studied the MYOC mutation (MYOCY437H)." (PMID 40965407, 2025). "The C-terminal olfactomedin (OLF) domain of myocilin houses ∼90% of disease-causing mutations, making the heritable subtype of glaucoma attractive for precision medicine and disease-modifying therapeutics." (PMID 39726989, 2025). "Mutations in the MYOC gene locus were the first glaucoma locus identified with a strong genetic link to POAG." (PMID 40385286, 2025). "Mutations of the aspartate at 380 are often pathogenic and associated with the development of glaucoma, as substitutions interfere with calcium binding and cause subsequent misfolding of the myocilin proteins." (PMID 40458333, 2025). "Such strategies are likely to provide more robust and consistent therapeutic outcomes in the context of MYOC-associated glaucoma." (PMID 41210166, 2025). "A key marker for assessing Dex-treated TM cells is the upregulation of myocilin, a protein encoded by the gene MYOC that is associated with the glucocorticoid (GC) response in TM cells and is linked to glaucoma pathogenesis." (PMID 40546349, 2025). "Mutations in the myocilin (MYOC) gene have long been implicated in glaucoma, contributing to 4% of POAG cases and accounting for over 30% of cases involving adult-onset juvenile glaucoma." (PMID 39516652, 2025). "Mutations in MYOC are the most common, well-established, and well-understood genetic causes of glaucoma." (PMID 41210166, 2025). "It is important to note that we only assessed a limited number of glaucoma-associated targets, and other glaucoma-associated genes, such as MYOC, would be valuable to pursue." (PMID 40650044, 2025). "Lipoplex encapsulating Cas9 and guide RNA targeting MYOC knocked out MYOC, reduced intracellular accumulation of mutant MYOC, and relieved ER stress, thereby rescuing a mouse model of MYOC-associated glaucoma." (PMID 41210166, 2025).
glaucoma (continued). "Individuals carrying MYOC p.Gln368Ter in the highest PRS tertile compared to the lowest tertile had a sixfold increased risk of glaucoma diagnosis and a younger age of diagnosis." (PMID 39929609, 2025). "More than 90% of glaucoma-associated MYOC gene mutations cluster within the olfactomedin domain, a conserved structural motif essential for MYOC structure and function." (PMID 41227293, 2025). "Here, we developed antibodies targeting the aggregation-prone β-propeller olfactomedin (OLF) domain of myocilin, variants of which comprise the strongest genetic link to glaucoma and cause early onset vision loss for several million individuals worldwide." (PMID 39726989, 2025). "In this study, we performed a simulated analysis of a glutamate-to-lysine substitution at position 414 (E414K) in the OLF domain of myocilin to explore the potential role of the variant in the pathogenesis of primary open-angle glaucoma." (PMID 40458333, 2025). "We next assayed the effect of anti-OLF1 and anti-OLF2 on cellular trafficking of a severe glaucoma-causing myocilin variant, P370L." (PMID 39726989, 2025). "Recent studies also emphasize the accumulation of somatic MYOC mutations related to age in the onset of glaucoma." (PMID 40385286, 2025). "In particular, UV-induced somatic C→T or G→A transition mutations within the MYOC coding region that lead to pathogenic MYOC missense or nonsense glaucoma variants are likely to be overexpressed in glaucomatous TM cells." (PMID 38397193, 2024). "Thermodynamically unstable pathologic germline mutations in MYOC lead to its overexpression in TM cells, which initiates a cascade of events that lead to glaucoma." (PMID 38397193, 2024). "MYOC genome analysis revealed a remarkable overlap between glaucoma-causing and cancer-associated mutations." (PMID 38397193, 2024). "A recent study shows a moderate correlation between the stability of inherited germline MYOC variants and the age at glaucoma diagnosis, which underlines the importance of the thermodynamic stability of mutated MYOC in activating the UPR pathway." (PMID 38397193, 2024). "Four of the glaucoma-causing mutations are stabilizing MYOC variants, and two of them overlap with cancer somatic mutations." (PMID 38397193, 2024). "Myocilin and cytochrome P450 1B1 (CYP1B1): Myocilin was the first gene identified to be linked to glaucoma." (PMID 38435218, 2024). "An analysis of MYOC somatic cancer-associated mutations revealed a notable overlap with pathogenic glaucoma variants." (PMID 38397193, 2024). "Topical administration of PBA has shown to reduce glaucomatous phenotypes in a mouse model of myocilin-associated glaucoma." (PMID 38315494, 2024). "About 105 germline mutations within MYOC are known to be associated with glaucoma and result in endoplasmic reticulum (ER) stress, which leads to trabecular meshwork (TM) cell death and subsequent intraocular pressure (IOP) elevation." (PMID 38397193, 2024). "Glaucoma is a highly heritable disease, and myocilin was the first identified causal and most common pathogenic gene in glaucoma." (PMID 38212635, 2024). "Our previous studies showed that N450Y or P370L mutation in MYOC leads to glaucoma phenotypes in transgenic mice models." (PMID 38212635, 2024). "Two recent studies focused on using CRISPR/Cas9 gene editing to alleviate ocular hypertension in MYOC-associated glaucoma." (PMID 39423611, 2024). "The hereditary aspect of POAG and MYOC, the initially identified disease-causing gene, plays a crucial role in the development of glaucoma, which has been shown in this study." (PMID 39809167, 2024). "Serine-to-proline mutation at position 341 of myocilin (MYOCS341P) is associated with severe glaucoma phenotypes in a five-generation primary open-angle glaucoma family." (PMID 38212635, 2024). "Our data generated from high-throughput analyses help elucidate the mechanism underlying mutant MYOC-related glaucoma." (PMID 38212635, 2024).
glaucoma (continued). "Glaucoma, especially its intricate variants, is linked to variants in genes like MYOC, OPTN, and TBK1." (PMID 39766826, 2024). "Because TM cells have the potential to accumulate somatic mutations at a rapid rate due to ultraviolet (UV) light exposure, we propose that an accumulation of somatic mutations within MYOC is an important contributor to the onset of glaucoma." (PMID 38397193, 2024). "Surprisingly, 2 MYOC rare variants in the signal peptide: p.(Cys5Trp) and p.(Gly12Arg) were detected in the present study, although less than 10% of glaucoma-related MYOC variants have been identified at the N-terminals." (PMID 39669598, 2024). "Approximately 5% of primary open-angle glaucoma cases in patients result from a mutation in the gene for myocilin, and it is expressed on higher levels in the trabecular meshwork." (PMID 38255979, 2024). "Mutations in the myocilin gene can lead to damage in the trabecular meshwork, thereby hindering the aqueous outflow and contributing to the onset of glaucoma." (PMID 38435218, 2024). "In adult POAG populations, the prevalence of myocilin mutations ranges between 3% and 5%, making it the most common form of inherited glaucoma currently known." (PMID 39456800, 2024). "Three genes associated with glaucoma have been identified within these loci: myocilin/trabecular meshwork glucocorticoid response (TIGR) (GLC1A), optineurin (GLC1E), and WDR36 (GLC1G)." (PMID 39456800, 2024). "We next visualized protein embeddings of glaucoma-associated genes and found that the human MYOC gene is embedded further away from the Myoc genes of the other species." (PMID 38366243, 2024). "Deleterious mutations, such as MYOC glaucoma-causing variants, reduce the folding efficiency of a protein and can induce protein aggregation, among other harmful responses." (PMID 38397193, 2024). "MYOC has been associated with juvenile and primary open-angle glaucoma (POAG) accounting for 2–5% of the POAG cases, and accounts for 5.5% of the PCG cases." (PMID 38755526, 2024). "MYOC is closely associated with glaucoma and has high expression levels in skeletal muscle and hearts in addition to the eye38." (PMID 38503760, 2024). "It has been reported that the severity of glaucoma in patients carrying different MYOC mutations varies." (PMID 38212635, 2024). "Herein, we analyze germline and somatic MYOC mutations obtained from glaucoma and cancer genomics databases." (PMID 38397193, 2024). "Somatic cancer-associated variants and germline neutral polymorphisms are spread evenly across the entire protein with frequent overlap; glaucoma-causing germline mutations largely localize to the OLF domain of MYOC." (PMID 38397193, 2024). "Studies have demonstrated that pathogenetic variants of MYOC can influence not only the severity but also the age of onset of glaucoma, making it a significant target for genetic and therapeutic research." (PMID 39766826, 2024). "In case yx9 with AD POAG caused by MYOC, the findings from numerous empirical studies corroborate the assertion that a gain-of-function mechanism plays a role in the pathogenesis of myocilin-associated glaucoma." (PMID 38785568, 2024). "One of the main reports of gene-supported precision medicine is the predictive gene testing for myocilin-associated glaucoma." (PMID 36769127, 2023). "Mutations in myocilin (MYOC) are the leading known genetic cause of primary open-angle glaucoma, responsible for about 4% of all cases." (PMID 38196579, 2023). "Mutations in myocilin are seen in glaucoma and lead to a blockage of the aqueous outflow via the trabecular meshwork, increasing the IOP." (PMID 37047335, 2023). "Genetic variants in the MYOC gene have been linked to the formation of glaucoma, and previous research primarily focused on aspects related to this." (PMID 36834493, 2023). "In the subset of patients with monogenic variants associated with glaucoma (MYOC variant (p.Gln368Ter), the PRS can further stratify individuals into high versus low risk groups." (PMID 37875865, 2023).